PGK1 (phosphoglycerate kinase 1)
Diseases named in the same sentence as PGK1 in open-access papers (continued):
Sharing a sentence is not in itself a finding about the gene and the disease.
prostate carcinoma (31 papers, 2010 to 2025). A carcinoma that arises from epithelial cells of the prostate gland. "Our work has highlighted GPI, PFKM, ALDOA, and PGK1 as key glycolysis-associated mRNAs that display CPSF1-dependent expression in prostate cancer cell lines." (PMID 39847481, 2025). "In public datasets, there was positive expression correlation between CUX1 and ENO1, GPI, or PGK1 in NB, colon cancer, or prostate cancer tissues, and their levels were associated with poor survival of tumor patients." (PMID 31709724, 2019). "This in turn results in the increased expression of TRIM68 and PGK-1 and these genes are associated with the progression of prostate cancer." (PMID 25647662, 2015). "CircROBO1 also contributes to enzalutamide resistance and glycolysis in prostate cancer through the circROBO1–miR-556-5p–PGK1 axis." (PMID 41229443, 2025). "The results revealed a progressive increase in both sLZIP and PGK1 protein levels as prostate cancer progressed." (PMID 39594816, 2024). "Since sLZIP promotes aerobic glycolysis and cell proliferation by regulating PGK1 expression in prostate cancer, we performed xenograft experiments using nude mice." (PMID 39594816, 2024). "sLZIP promotes the transcription of PGK1, leading to lactate accumulation and consequently facilitating the progression of androgen-independent prostate cancer cells." (PMID 39594816, 2024). "Since both knockout and transient silencing of sLZIP in the PC3 cells resulted in a decrease in PGK1 mRNA expression, we further analyzed the effect of sLZIP deprivation on PGK1 expression in prostate cancer." (PMID 39594816, 2024). "Our study indicates that sLZIP promotes lactate secretion via PGK1 by enhancing the glycolytic activity of prostate cancer cells." (PMID 39594816, 2024). "miR-143 suppresses phosphoglycerate kinase-1 (PGK1), which is associated with the progression of prostate cancer." (PMID 39445208, 2024). "In prostate cancer, extracellular PGK1 has disulfide reductase activity against fibrinolytic enzymes, leading to elevated plasma levels of angiostatin, thereby inhibiting angiogenesis and tumour growth." (PMID 37723547, 2023). "PGK1 was extremely upregulated in prostate cancer cell lines compared to normal cell WPMY1, especially in C4-2B and 22RV1 prostate cancer cell lines, determined by RT-qPCR analysis." (PMID 37670963, 2023). "According to our results, PGK1 was extremely decreased after the inhibition of circROBO1 in C4-2B and 22RV1 prostate cancer cells." (PMID 37670963, 2023). "Next, we used RT-qPCR to verify the expression level of the PGK1 expression level in ten pairs of prostate cancer tissues and adjacent normal tissues." (PMID 37670963, 2023). "We found that circROBO1, miR-556-5p, and PGK1 mRNA were all enriched to RNA induced silencing complex in both C4-2B and 22RV1 prostate cancer cells, assessed by the anti-Ago2 related RIP assays." (PMID 37670963, 2023). "miR-215-5p, for example, inhibits prostate cancer metastasis by targeting PGK1, whereas miR-671-5p increases prostate cancer metastasis by targeting the NFIA/CRYAB axis." (PMID 36884182, 2023). "In prostate cancer (PCa), PGK1 expression is upregulated, and its expression is negatively regulated by miRNA-215-5p." (PMID 37723547, 2023). "Then, we also detected the expression level of PGK1 in prostate cancer lines using RT-qPCR analysis." (PMID 37670963, 2023). "In conclusion, our study identified the biological role of circROBO1 in the growth and enzalutamide resistance of prostate cancer through the miR-556-5p-PGK1- glycolysis axis." (PMID 37670963, 2023). "To further validate the mechanism of circROBO1-miR-556-5p-PGK1 axis in regulating prostate cancer enzalutamide resistance and glycolysis, we conducted several rescue assays." (PMID 37670963, 2023).
prostate carcinoma (continued). "In prostate cancer, PGK1 has been demonstrated to promote MMP-2 and MMP-9 expression in normal fibroblasts (NSFs), resulting in induction of the phenotypic transformation of NSFs into cancer-associated fibroblasts (CAFs)." (PMID 37723547, 2023). "An important link between PGK1 expression and CXCR4/CXCL12 has been reported in prostate cancer cells, where overexpression of PGK1 increases the cell metastasis rate." (PMID 37723547, 2023). "Overexpression of PGK1 in prostate cancer cells has been reported to increase cell metastasis through the CXCR4/CXCL12 axis." (PMID 36860848, 2023). "Prostate cancer cells release PGK1, which regulates bone metastatic activity by increasing osteoblastic activity and decreasing osteoclastic function." (PMID 36276080, 2022). "Overexpression of PGK1 facilitates not only tumor growth and interaction with microenvironment, but tumor invasion and metastasis in liver, gastric and prostate cancer." (PMID 32241274, 2020). "A potential mechanism underlying the anti-prostate cancer activity of SIF is its promotion of miR-29a and miR-1256, leading to down-regulation of TRIM68 and PGK-1 by inhibiting methylation of the miR-29a and miR-1256 promoters." (PMID 31178721, 2019). "GM+CTCs (marked by PGK1/G6PD) were detectable in 64.8% (35/54) of prostate cancer patients, accounting for 46.5% (134/288) of total CTCs." (PMID 29954422, 2018). "Phosphoglycerate kinase 1 (PGK1) is one of the proteins up-regulated in the radioresistant prostate cancer cell lines, which is known to have roles in both DNA replication and repair in mammalian cells." (PMID 23990015, 2014). "Recent studies suggest that prostate cancer cell-derived PGK-1 induces osteoblastic differentiation of bone marrow stromal cells, affecting bone formation at the metastatic site." (PMID 24423398, 2013). "A close relationship between the regulation of the CXCR4/SDF1 axis and PGK1 has been shown for prostate cancer, influencing the “angiogenic switch” through the regulation of angiostatin." (PMID 24376734, 2013). "This determines a close relationship between the regulation of the CXCR4/SDF1 axis and PGK1 in prostate cancer." (PMID 24376734, 2013). "As sLZIP induces the transcription of PGK1, we investigated whether sLZIP contributes to aerobic glycolysis in prostate cancer." (PMID 39594816, 2024). "In addition, both sLZIP and PGK1 expression are higher in androgen-independent prostate cancer cells compared to androgen-dependent prostate cancer cells." (PMID 39594816, 2024). "Since sLZIP acts as a transcription factor in various cellular processes, we examined whether sLZIP regulates the transcription of PGK1 in prostate cancer." (PMID 39594816, 2024). "However, further studies are needed to verify the effect of sLZIP-induced PGK1 expression in androgen-dependent prostate cancer cells." (PMID 39594816, 2024). "Generally, our study identified the biological role of the circROBO1-miR-556-5p-PGK1 axis in the growth and enzalutamide resistance of prostate cancer, which could be an effective therapeutic target." (PMID 37670963, 2023). "In prostate cancer, circ_0076305 serves as a novel oncogene by regulating the miR-411-5p/PGK1 axis." (PMID 37723547, 2023). "Furthermore, both C4-2B and 22RV1 prostate cancer cell lines revealed a decrease in PGK1 mRNA gathering to RISC complexes after targeting circROBO1." (PMID 37670963, 2023). "Gene expression analysis of CTCs of prostate cancer patients have revealed altered expression levels of eight metastasis-related metabolic genes, such as phosphoglycerate kinase 1 (PGK1) and glucose-6-phosphate dehydrogenase (G6PD) responsible for optimal glucose metabolism in CTCs." (PMID 33924671, 2021).
prostate carcinoma (continued). "Demethylation of these promoters leads to the decrease in expression of TRIM68 and PGK1 in prostate cancer cells, whilst methylation of the promoter of miRNA-29a led to increased expression of Myeloid cell leukemia sequence 1 (Mcl-1) which blocks apoptosis and supports cell survival in lymphoma." (PMID 25647662, 2015). "Thus, sLZIP promotes aerobic glycolysis in prostate cancer cells by regulating PGK1 expression." (PMID 39594816, 2024). "The study validated two key PPARγ target genes, PRKCZ and PGK1, which were repressed upon PPARγ activation by its natural ligand, 15d-PGJ2, in three prostate cancer cell lines." (PMID 39065726, 2024). "During hypoxia, STAT3 and HIF-1α cooperatively activate HIF-1α target genes, VEGF, phosphoglycerate kinase 1 (PGK1), and carbonic anhydrase 9 (CA9) in prostate cancer cells." (PMID 28978186, 2017). "Further, PGK1/G6PD-marked hypermetabolic CTCs (GM+CTCs, i.e. DAPI+CD45−PGK1/G6PD+ cells) potentially represent a more accurate marker than EMT-CTCs for the diagnosis of metastasis in prostate cancer patients." (PMID 35992829, 2022). "Further, CUR can significantly increase miR-143 and decrease PGK1 expression, while ectopic expression of FOXD3 can enhance the regulatory effect of CUR on miR-143, thereby inhibiting the proliferation and migration of prostate cancer cells." (PMID 31178721, 2019). "However, in-depth research focused on the role and regulation of PGK1 in prostate cancer metabolism has not been extensively explored and remains to be elucidated." (PMID 39594816, 2024). "Increased sLZIP may induce PGK1 expression, which may promote aerobic glycolysis and promote prostate cancer progression in the absence of androgen signaling." (PMID 39594816, 2024).
colon carcinoma (30 papers, 2014 to 2025). "Furthermore, blocking O-GlcNAcylation via the PGK1-T255V mutation inhibits colon cancer cell proliferation in vitro and retards tumor growth in vivo." (PMID 39178944, 2024). "Interestingly, increased expression of PGK1 in colon cancer tissue has been associated with metastasis in a cohort of patients with colon cancer." (PMID 32230855, 2020). "In conclusion, these results demonstrated that cell proliferation and glycolysis of colon cancer cells inhibited by NAT10 knockdown was partially restored by PGK1 overexpression." (PMID 41426311, 2025). "Previous studies have reported that post-translational modification of PGK1 protein stabilize its expression, thereby enhancing cancer glycolysis, including in colon cancer." (PMID 41426311, 2025). "Taken together, this study demonstrated that emodin inhibited the tumor growth of colon cancer by suppressing glycolysis in tumor cells through inhibiting NAT10-mediated ac4C modification of PGK1." (PMID 41426311, 2025). "Mechanistically, NAT10 promotes glycolysis of colon cancer cells by stabilizing PGK1 expression through enhancing ac4C modification on PGK1." (PMID 41426311, 2025). "Then, we detected the function of PGK1 by transfecting pcDNA3.1-PGK1 into colon cancer cells, and its mRNA expression and protein levels were increased in HCT-116 and SW480 cells." (PMID 41426311, 2025). "In this study, we demonstrated that NAT10 stabilized PGK1 mRNA through enhanced ac4C modification on PGK1, thereby promoting glycolysis and cell proliferation in colon cancers." (PMID 41426311, 2025). "It has been discovered that PGK1 has oncogenic properties and is amplified in various human cancers, including renal clear cell carcinoma, ovarian cancer, breast cancer, colon cancer, and liver cancer." (PMID 38163864, 2024). "In human colon cancer cells, PGK1 has been identified as a potential biomarker that reflects intracellular oxidative stress status, and antioxidants can inhibit the expression of HIF-1ɑ and PGK1." (PMID 37723547, 2023). "The expression of PGK1 in colon cancer tissues from metastatic patients increased by 2.6-fold compared with that of patients with no metastasis." (PMID 38136210, 2023). "For example, O‐GlcNAcylation activates PGK1 led to enhance glycolysis, and finally promote tumorigenesis in colon cancer." (PMID 36366731, 2023). "Phosphoglycerate kinase 1 (PGK1), an essential enzyme of glycolysis, is highly expressed in colon cancer and is associated with increased cell proliferation, as well as with resistance to chemoradiotherapy and overall poor patient prognosis." (PMID 37838167, 2023). "Conversely, blocking O-GlcNAcylation of PGK1 decreases cell proliferation and suppresses glycolysis in colon cancer cells." (PMID 37838167, 2023). "In fact, blocking T255 O-GlcNAcylation of PGK1 decreases colon cancer cell proliferation, suppresses glycolysis, promotes the TCA cycle, and inhibits tumour growth in xenograft models." (PMID 37723547, 2023). "To investigate the possible role of PGK1 in colon cancer development and progression, we analyzed PGK1 protein expression levels in 50 peritumoral/tumor tissue pairs from colon cancer patients." (PMID 31911580, 2020). "We observed that 27 pairs of samples showed higher levels of OGT expression in cancer tissues compared to the matched tissues, indicating that OGT expression positively correlates with PGK1 glycosylation levels in colon cancer." (PMID 31911580, 2020). "Blocking T255 O-GlcNAcylation on PGK1 suppresses the Warburg effect, decreases colon cancer cell proliferation, and inhibits tumor growth in nude mice." (PMID 31911580, 2020). "Blocking T255 O-GlcNAcylation of PGK1 decreases colon cancer cell proliferation, suppresses glycolysis, enhances the TCA cycle, and inhibits tumor growth in xenograft models." (PMID 31911580, 2020). "Next, we analyzed PGK1 expression levels using a panel of colon cancer cell lines and two normal colon cell lines NCM460 and CRYPT." (PMID 31911580, 2020).
colon carcinoma (continued). "We found that PGK1 T255V rescue RKO, LoVo and HT-29 cells showed a significant decrease in cell proliferation compared to their corresponding PGK1 WT rescue cells, suggesting that T255 glycosylation is functionally important in colon cancer cells." (PMID 31911580, 2020). "All of the seven colon cancer cell lines displayed higher PGK1 expression levels compared to the normal cell lines, which was consistent with high PGK1 expression in clinical tumor tissue samples." (PMID 31911580, 2020). "A total of 50 pairs of primary human colon cancer tissue samples with the matched adjacent normal tissues were collected, and PGK1 glycosylation levels were determined." (PMID 31911580, 2020). "To gain a better understanding of the impact of PGK1 O-GlcNAcylation on colon cancer, we first examined the glycosylation levels using a panel of three human colon cancer cell lines and a normal colon cell line NCM460." (PMID 31911580, 2020). "To probe the clinical relevance of PGK1 glycosylation, we examined O-GlcNAcylation levels of PGK1 in human colon cancer tissues." (PMID 31911580, 2020). "To investigate the possible role of PGK1 in colon cancer cells, we depleted PGK1 with small hairpin RNA (shRNA) in LoVo, HCT-116, and HT-29 cells, and observed a significant reduction in cell proliferation in all three cell lines." (PMID 31911580, 2020). "In conclusion, we demonstrated that emodin inhibited tumor growth of colon cancer by suppressing glycolysis in tumor cells through inhibiting NAT10-mediated ac4C modification of PGK1, indicating that emodin is an effective medicine for treatment of colon cancer." (PMID 41426311, 2025). "In the context of colon cancer, it has been confirmed that PGK1 may undergo reversible and dynamic modification with O-GlcNAc at threonine 255 (T255)." (PMID 38163864, 2024). "Oxidants induce PGK1 expression in cultured human colon carcinoma cells and hepatoblastoma cells." (PMID 37226192, 2023). "Phosphoglycerate kinase 1 is considered as a promoter of metastasis in colon cancer." (PMID 35327385, 2022). "For example, O‐GlcNAcylation of PGK1 at threonine 255 regulates the glycolysis and promotes the development of colon cancer, acetylation of PGK1 at K323 contributes to liver progression, phosphorylation of PGK1 at Y324 devote to glioblastoma multiforme formation." (PMID 34337858, 2021). "To determine whether PGK1 O-GlcNAcylation correlates with colon cancer progression, we grouped the 23 paired samples according to the stages and compared PGK1 glycosylation levels between different groups." (PMID 31911580, 2020). "Moreover, O-GlcNAcylation of PGK1 is significantly elevated in human colon cancer tissues compared with the adjacent matching tissues." (PMID 31911580, 2020). "PGK1 glycosylation was observed elevated in all three colon cancer cell lines compared to NCM460." (PMID 31911580, 2020). "PGK1 is a promoter of metastasis in colon cancer, which might be a potential protein biomarker of intracellular oxidative status in human colon carcinoma cells." (PMID 28749413, 2017). "PGK1 might be an advisable target molecule for specific immunotherapy of HLA-A2+ colon cancer patients." (PMID 28749413, 2017). "Several glycolysis genes, including glyceraldehyde-3-phosphate dehydrogenase, phosphoglycerate kinase 1 and phosphoglycerate mutase 1, have up-regulation in colon cancer tissues, therefore colon cancer cells have a higher glycolytic rate compared with normal cells." (PMID 24935220, 2014). "Mechanistically, the O-GlcNAcylation of PGK1 at Thr-255 not only increases PGK1 kinase activity to increase lactate production but also triggers the translocation of PGK1 into mitochondria to phosphorylate and inhibit pyruvate dehydrogenase in colon cancer cells." (PMID 39178944, 2024). "Furthermore, PGK1 O-GlcNAcylation levels are elevated in human colon cancers." (PMID 31911580, 2020). "However, whether PGK1 is mediated by NAT10 in colon cancer remain unclear." (PMID 41426311, 2025).
colon carcinoma (continued). "In liver cancer, PGK1 suppresses cell death through modulation of PRAS40, while in colon cancer, it upregulates the expression of EGR1, a metastasis-related factor." (PMID 38163864, 2024). "All these proteins, with the exception of phosphoglycerate kinase 1, were found oxidized after Auranofin treatment in HT29 colon cancer cells indicating that gold carbene complexes behave similar to this typical and well-characterized gold(I) complex." (PMID 35543764, 2022). "In colon cancer cases, a positive correlation between SPIB and HK2 expression was noted (R = 0.1441, p < 1 × 10−4) or PGK1 (R = 0.3072, p < 1 × 10−4) and high levels of SPIB (p = 1.5 × 10−2) were linked with poor prognosis of colon cancer patients." (PMID 34841706, 2021). "Thus, our data suggest that PGK1 O-GlcNAcylation may be critical for colon cancer development." (PMID 31911580, 2020). "Next, we examined the change in PKC coding genes in colon cancer tissue when the data was normalised to one RG, PGK1, and normalised to three RGs, PGK1, GUSB and PP1A." (PMID 26962435, 2016). "The last reference gene, the glycolysis enzyme phosphoglycerate kinase 1 (PGK1), is a target gene of both the myc oncogene pathway and the hypoxia inducible factor 1α (HIF-1α) and is therefore considered as a marker gene for a number of malignant tissues such as kidney cancer or colon cancer." (PMID 26468005, 2015).